WFDC5 (WAP four-disulfide core domain 5)
Description:
Putative acid-stable proteinase inhibitor.
Synonyms: PRG5; WAP1; dJ211D12.5
Tractability: Antibody: UniProt places it where antibodies can reach, with high confidence; UniProt predicts a signal peptide or a membrane-spanning region; its Gene Ontology location is reachable by antibodies, with medium confidence.
Gene: Protein-coding gene on chromosome 20 (45,109,452 to 45,115,174, reverse strand). Ensembl gene ENSG00000175121.
Subcellular location: Secreted
Gene Ontology:
Molecular function: protein binding; serine-type endopeptidase inhibitor activity; peptidase inhibitor activity
Biological process: antibacterial humoral response; innate immune response
Cellular component: extracellular region
Genetic constraint (gnomAD): Loss-of-function variants: 15 observed, 15.77 expected, observed/expected ratio (o/e) 0.95, 90% interval 0.63 to 1.46. The upper end of that interval is the gene's LOEUF score, 1.46, which puts it in group 6 of 6, group 1 being the genes least tolerant of losing a copy. Missense variants: 194 observed, 203.09 expected, observed/expected ratio (o/e) 0.96, 90% interval 0.85 to 1.08. Synonymous variants: 79 observed, 83.73 expected, observed/expected ratio (o/e) 0.94, 90% interval 0.79 to 1.14.
Homologues: Orthologues: chimpanzee WFDC5 (100% identical), macaque WFDC5 (95% identical), pig WFDC5 (78% identical), rabbit WFDC5 (73% identical), dog WFDC5 (72% identical), guinea pig WFDC5 (69% identical), mouse Wfdc5 (67% identical), rat Wfdc5 (59% identical), Drosophila melanogaster CG5639 (39% identical), Caenorhabditis elegans C08G9.2 (29% identical). Paralogues in human: WFDC3 (35% identical), SLPI (33% identical), PI3 (24% identical), WFDC12 (20% identical), WFDC10A (16% identical), WFDC10B (15% identical), WFDC13 (15% identical), WFDC9 (15% identical), WFDC11 (12% identical).
Diseases named in the same sentence as WFDC5 in open-access papers:
WFDC5 is named in the same sentence as 4 diseases in open-access papers, as found by Europe PMC text mining. Sharing a sentence is not in itself a finding about the gene and the disease. The quoted sentences say what the papers report.
lung carcinoma (2 papers, 2012 to 2025). "Our transcriptomic analysis revealed strong up-regulation of the WFDC2 and WFDC5 genes by A+N in A549 lung cancer cell lines and strong synergy between these two drugs in the up-regulation of these genes." (PMID 40362653, 2025). "Consistent with this conclusion, in another lung cancer cell line, NCI-H460, A+N only strongly up-regulates WFDC5 from zero expression in control cells." (PMID 40362653, 2025).
tumor (2 papers, 2022 to 2025). "SLPI, WFDC2, WFIKKN2, and WFDC1 consistently showed low expression across tumor types, whereas WFDC5, WFDC3, and WFIKKN1 displayed heterogeneous expression profiles." (PMID 40350979, 2025).
WFDC5 also shares sentences with these, for which no sentence is quoted: cancer (2 papers); melanoma (1).